RIPK3 (receptor interacting serine/threonine kinase 3)
Diseases named in the same sentence as RIPK3 in open-access papers (continued):
Sharing a sentence is not in itself a finding about the gene and the disease.
colon carcinoma (continued). "Similarly, a pair of mouse cell lines with high (BW5147, TCL) and low (CT26, colon cancer) basal levels of RIPK3 expression were treated for 2 days with decitabine and levels of RIPK3 measured." (PMID 38727208, 2024). "In some diseases, such as colon cancer and Cowpox virus infection, the expression of RIPK3 could be regulated through transcription mechanisms." (PMID 35110556, 2022). "RIPK3 increases after being exposed to heat and prompts necroptosis in colon cancer cells." (PMID 35884370, 2022). "HPA3P induces necroptosis in colon cancer cells depending on RIPK3 and MLKL." (PMID 35884370, 2022). "In addition, the expression of RIPK3 was increased in tumour tissue extract of HPA3P-treated mice, which is consistent with an increase in RIPK3 by HPA3P in colon cancer cells." (PMID 29487701, 2018). "Finally, we measured RIPK3 expression in the colon cancer cells used in this experiment and confirmed that protein and mRNA of RIPK3 were expressed in all cells." (PMID 29487701, 2018). "Thus, our results reveal that the necroptosis adaptor RIPK3 has key anti-inflammatory and anti-tumoral functions in the intestine, and define RIPK3 as a novel colon tumor suppressor." (PMID 27344176, 2016). "Given the increased expression of pro-inflammatory and pro-tumorigenic factors in colonic tumors of Ripk3−/− mice, we wanted to examine whether RIPK3 regulates proliferation of IECs following AOM-DSS treatment." (PMID 27344176, 2016). "We found that the number of colon tumors was significantly increased in Ripk3−∕− mice." (PMID 27446921, 2016). "Indeed, we found that RIPK1 and RIPK3 are largely dispensable for colon cancer cell death induced by many common chemotherapeutic agents." (PMID 25675296, 2015). "Interestingly, transcription of Ripk1 and Ripk3 was controlled by hypoxia, suggesting that hypoxia may be one of the mechanisms that regulate Ripk1 and Ripk3 expression in human colon cancer tissues." (PMID 25675296, 2015). "However, the loss of RIPK1 and RIPK3 expression in colon cancer was not due to epigenetic DNA modification." (PMID 25675296, 2015). "The exposition of HCT116 (adult male with colon cancer) and HT29 to PmPOD induced interactions between RIPK1 and RIPK3, which consequently initiated necroptosis." (PMID 41303584, 2025). "RIPK1/RIPK3-MLKL signaling molecules are fundamental in initiating necroptotic cell death, but their roles in the development of colon cancer are unclear." (PMID 39540935, 2024). "Instead, caspase inhibitors and/or second mitochondria-derived activators of caspase mimetic are needed to sensitize colon cancer cells to RIPK1 and RIPK3." (PMID 35884370, 2022). "Gut epithelial TSC1/mTOR reduces necroptosis by inhibiting the expression and activation of RIPK3, thus preventing IBD and even colon cancer." (PMID 35884370, 2022). "Instead of targeting the three major proteins, PARP-1, a downstream active effector of RIPK1/RIPK3, can be activated by TRAIL and induce necroptosis in colon cancer cells." (PMID 35884370, 2022). "Cobalt chloride and GLTP overexpression rely on RIPK1, RIPK3, and MLKL to induce necroptosis in colon cancer cells." (PMID 35884370, 2022). "Also, Ripk3−/− animals with dysplasia had higher inflammation scores than WT mice with dysplasia, which is in line with the concept that inflammation-related genes, transcribed by one of the key transcription factors NF-κB, prominent in inflamed mucosa remain elevated in colonic neoplasms." (PMID 27344176, 2016). "Here we show that RIPK1 and RIPK3 expression is significantly decreased in human colon cancer tissues, suggesting that suppression of RIPK1 or RIPK3 expression is advantageous for cancer growth." (PMID 25675296, 2015).
colon carcinoma (continued). "The MTOR/RIPK3/necroptosis axis is an initiator of IBD and colon cancer." (PMID 35884370, 2022). "Moreover, in colon cancer cells, by cooperating with RIPK1/RIPK3, ROS can facilitate cytosolic calcium accumulation and give rise to striking necroptosis." (PMID 35222645, 2022). "In colon cancer, the expression of RIPK1 and RIPK3 is significantly decreased due to hypoxia." (PMID 31766571, 2019). "It is noteworthy that many breast and colon tumors do not express RIPK3, while pancreatic cancers often exhibit increased RIPK1 and RIPK3 expression." (PMID 27446921, 2016). "By treating human colon cancer HT-29 cells with TNF-α, about 200,000 chemical compounds were screened for their ability to inhibit necroptosis, and MLKL was identified as a critical substrate of RIPK3 during the induction of necroptosis." (PMID 27429198, 2016). "We found that chemotherapeutic agents did not effectively elicit RIPK1/RIPK3-dependent necroptosis in colon cancer cells." (PMID 25675296, 2015). "Based on the levels of RIPK3 and SPOP endogenous expression in colon cancer cell lines, including HT-29, HCT115, DLD-1, HCT116, WiDr, and SW480, HT-29 cells were selected for further experiments because they exhibited detectable levels of RIPK3 and SPOP, making them suitable for the present study." (PMID 39540935, 2024). "However, in colon cancer, the loss of RIPK1 and RIPK3 expression was found not to be due to epigenetic DNA modification." (PMID 36849530, 2023). "We previously reported that CRISPR/Cas9-mediated knockout (KO) of USP22 in the human colon carcinoma cell line HT-29 affects RIPK3 ubiquitination during necroptosis without inducing major changes in RIPK1, RIPK3, and MLKL gene expression, suggesting gene-specific regulation of USP22." (PMID 35933402, 2022). "Regarding the expression of the molecular effectors of necroptosis in tumors, some studies reported a decreased expression of RIPK3, but not RIPK1, in AML, while deficiency of both RIPK3/RIPK1 has been reported in colon cancer as compared to non-malignant adjacent tissues." (PMID 34490126, 2021).
myocardial infarction (29 papers, 2015 to 2025). Gross necrosis of the myocardium, as a result of interruption of the blood supply to the area, as in coronary thrombosis. "RIPK3 phosphorylates CaMKII and increases myocardial ROS production which will cause the myocardial infarction." (PMID 34867386, 2021). "On the other hand, a deficiency of RIPK3 not only attenuated the death rate of cardiomyocytes in cardiac ischemia reperfusion injury mice, but also improved the symptoms of myocardial infarction and systemic inflammation induced by high-dose TNF-α or A20 deficiency." (PMID 31248365, 2019). "The hypoxic injury and myocardial infarction (MI) are associated with increased RIPK3 expression, leading to inactivation of AMPK." (PMID 34336092, 2021). "In line with these notions, the dysregulation of RIPK3 may play an indispensable role in the development of necroptosis-associated diseases, which are presented as myocardial infarction, and RIPK3 may be a candidate target for new drug designs against these diseases." (PMID 31248365, 2019). "Studies using RIPK3-deficient mice have implicated pathological RIPK3 signaling, and potentially necroptosis, in many inflammatory diseases, such as atherosclerosis, kidney ischemia reperfusion injury, liver injury, myocardial infarction, and multiple sclerosis (reviewed in9)." (PMID 27158445, 2015). "Ablation of the RIPK3 gene improves cardiac function and survival in a murine model of myocardial infarction 33854696, which suggests that RIPK3-dependent necroptosis plays an important pathogenic role in heart failure." (PMID 40650199, 2025). "In a mouse model, microRNA-325-3p protects the heart from I/R injury after myocardial infarction by inhibiting RIPK3 and necroptosis." (PMID 37504559, 2023). "It was reported that miR-325-3p protected the mouse heart after myocardial infarction through inhibiting RIPK3 and programmed necrosis." (PMID 35136419, 2022). "The expression level of RIPK3 was further upregulated in myocardial tissue after myocardial infarction in a mouse model of coronary artery ligation and in myocardial cells after hypoxic injury in vitro." (PMID 36132224, 2022). "A significant increase in the expression of RIPK3 mRNA and its phosphorylated protein can also be observed after myocardial infarction in rodents." (PMID 35805993, 2022). "Receptor-interacting protein 3- (RIPK3-) modulated necroptosis plays a critical role in cardiac remodelling after myocardial infarction (MI)." (PMID 33854696, 2021). "RIPK3−/− mice undergoing left anterior descending coronary artery ligation developed a myocardial infarction and showed better ejection fraction and less hypertrophy." (PMID 34867386, 2021). "RIPK1 and RIPK3 mRNA and phosphorylated protein levels have been found to be significantly elevated in cardiac tissue from rodents after myocardial infarction." (PMID 33142926, 2020). "Receptor-interacting serine-threonine kinase 3 (RIPK3)-mediated necroptosis has been implicated in the progression of myocardial infarction (MI), but the underlying mechanisms, particularly whether microRNAs (miRNAs) are involved, remain largely unknown." (PMID 31248365, 2019). "The derepression of RIPK3 may reconcile the contribution of necroptosis in inflammatory disorders such as hepatocellular carcinoma, acute myocardial infarction, acute ischemic stroke and kidney ischemia-reperfusion injury." (PMID 38750308, 2024). "Myocardial infarction and ischemia-reperfusion injury are related to RIPK3-dependent necroptosis." (PMID 34867386, 2021). "In addition, RIPK3-mediated necroptosis regulated by CaMKII can conduct in specific processes of myocardial infarction." (PMID 34867386, 2021). "Several studies suggest that circulating RIPK3 could be a meaningful biomarker in acute myocardial infarction." (PMID 33142926, 2020).
myocardial infarction (continued). "However, kidney ischemia-reperfusion injury, myocardial infarction, and systemic inflammation associated with A20 deficiency or high-dose tumor necrosis factor (TNF) were ameliorated by RIPK3 deficiency." (PMID 28423682, 2017). "Moreover, suppression of lncRNA NRF could antagonize RIPK1/RIPK3-mediated necrosis in cardiomyocytes and reduce necrosis and myocardial infarction upon ischemia/reperfusion (I/R) injury in the animal model by targeting miR-873." (PMID 35091561, 2022). "Arctiin significantly reduced myocardial I/R injury (myocardial infarction and creatine kinase release), while decreasing the levels of necroptosis-related proteins (RIPK1/p-RIPK1, RIPK3/p-RIPK3, and MLKL/p-MLKL) in the hearts of I/R-treated rats." (PMID 37504559, 2023). "Simultaneously, knockdown of the RIPK3 gene can induce AMPK/Parkin-mediated mitophagy activation, which ultimately inhibits mPTP opening, alleviates cardiac remodeling after myocardial infarction (MI), and inhibits cardiomyocyte necroptosis." (PMID 36132224, 2022). "FADD upregulation promoted necrosis and improved myocardial infarction by influencing the formation of RIPK1 and RIPK3 complexes." (PMID 36348274, 2022). "In the acute IRI mouse model, RIPK3 deletion protects the heart from necroptosis induced by IRI and reduces the area of myocardial infarction (MI)." (PMID 34977874, 2021). "Attention has also been paid to the role of RIPK3, which lies downstream of RIPK1 in the necroptosis signaling cascade, in myocardial infarction." (PMID 33142926, 2020). "Unfortunately, due to cytotoxicity, the efficacy of RIPK3 specific inhibitors in reducing myocardial infarct severity has not been able to be tested." (PMID 33142926, 2020). "However, to our best knowledge, few studies that have focused on the mechanism of miRNAs in myocardial infarction have been reported, particularly through the pathways involving RIPK1/RIPK3." (PMID 31248365, 2019).
atherosclerosis (28 papers, 2015 to 2026). A disease characterized by the build-up of fatty material and calcium deposition in the arterial wall resulting in partial or complete occlusion of the arterial lumen. "While the lipid profile of Casp8komac mice was more favorable with respect to atherosclerosis, this aligns with recent findings that caspase-8 deficiency in myeloid cells, coupled with Ripk3 knockout, results in lower plasma cholesterol levels." (PMID 40264785, 2025). "Receptor-interacting protein kinase 3 (RIPK3) was recently implicated in promoting atherosclerosis progression through a proposed role in macrophage necroptosis." (PMID 31953345, 2020). "However, as previous studies have already linked RIPK3 and atherosclerosis, we suspected that this low Ripk3 transcript copy number did not accurately predict RIPK3 activity in the aorta." (PMID 31953345, 2020). "Diseases such as Alzheimer’s disease, epilepsy, type II diabetes, systemic lupus erythematosus, and atherosclerosis are all associated with local accumulation of pro-inflammatory neutrophils, and thus might be potential applications for Ripk3-targeted treatments." (PMID 35220408, 2022). "However, owing to the fact that RIPK1 plays roles in regulating necroptosis, apoptosis, autophagy, inflammation and cell survival pathways, it is difficult to speculate how the substantial decrease in RIPK1 affects atherosclerosis in Ripk3-deficient animals." (PMID 31953345, 2020). "Considering that Ripk3 deletion in different cardiac cell types impacts atherosclerosis differently in Apoe−/− mice, our future studies will investigate the cell type- and tissue-specific effects of Mlkl in aging." (PMID 39930289, 2025). "Taken together, these findings provide new mechanistic insights into tar-induced atherosclerosis progression and identify RIPK3 as a potential therapeutic target to prevent atherosclerosis in individuals who have not successfully quit smoking." (PMID 38229167, 2024). "The findings revealed that cigarette tar promoted atherosclerosis progression by inducing RIPK3-dependent VSMC necroptosis and identified novel avenues of ER stress and Ca2+ overload." (PMID 38229167, 2024). "Our findings provide new insights into the pathogenesis of smoking-affected atherosclerosis and will aid in identifying a novel therapeutic target of RIPK3 to prevent atherosclerosis progression in smoking patients." (PMID 38229167, 2024). "In this study, by employing ApoE−/− mice and specific genetic deletion mice (RIPK3−/−), we aimed to determine the effect and molecular mechanisms of tar on VSMCs and atherosclerosis progression." (PMID 38229167, 2024). "Intriguingly, RIPK3 in macrophages and endothelial cells (ECs) protects against atherosclerosis through necroptosis‐independent mechanisms." (PMID 38873710, 2024). "Our data illustrated that cigarette tar exacerbates atherosclerosis, which was attenuated by genetic deletion of RIPK3." (PMID 38229167, 2024). "In mouse models of atherosclerosis, such as LDL receptor deficiency or ApoE deficiency, genetic ablation of RIPK3 reduces both advanced atherosclerotic lesions and lesional inflammation." (PMID 39872161, 2022). "Abnormal activation of Ripk3 signaling is involved in many aging-related diseases, such as atherosclerosis, stroke, and leukemia." (PMID 35561683, 2022). "Disease Models & Mechanisms (DMM) is delighted to announce that the winner of the DMM Prize 2020 is Sarah Colijn, for her paper entitled 'Cell-specific and athero-protective roles for RIPK3 in a murine model of atherosclerosis'." (PMID 33973624, 2021). "Necroptotic cell death found in the necrotic core within atherosclerotic lesions provides the possibility of RIPK1/RIPK3-mediate necroptosis signaling pathway investigation in atherosclerosis." (PMID 34867386, 2021). "Conversely, genetic deletion of endothelial Ripk3 impairs developmental angiogenesis and exacerbates vascular lesion formation in a murine atherosclerosis model." (PMID 34153072, 2021).
atherosclerosis (continued). "To explore the cell-specific function of RIPK3 in the vasculature, and to confirm which cell types – if any – undergo necroptosis in atherosclerosis, we developed a conditional model of Ripk3 deletion that utilizes a Ripk3 locus integrated with loxP sites." (PMID 31953345, 2020). "In humans and preclinical models of disease, necroptosis has been shown to be activated in atherosclerotic plaques, and the damaging roles of RIPK1 and RIPK3 in atherosclerosis formation are beginning to come to light." (PMID 33142926, 2020). "We conducted this study by using the Ripk3-floxed mice crossed with macrophage-, vascular smooth muscle cell- and endothelial cell-specific Cre recombinases on the Apoe−/− murine model of atherosclerosis." (PMID 31953345, 2020). "A major finding from our study is that RIPK3 plays unexpected anti-inflammatory roles in atherosclerosis and contributes to the athero-protection of the descending and abdominal aortic regions." (PMID 31953345, 2020). "We now report that RIPK3 plays a biologically relevant role in atherosclerosis in macrophages and endothelial cells through an athero-protective – and likely non-necroptotic – mechanism." (PMID 31953345, 2020). "To explore the role of RIPK3 in the various cell types of atherosclerosis, we first attempted to look at RIPK3 expression in the plaque regions." (PMID 31953345, 2020). "When Ripk3 is genetically deleted in a murine model of atherosclerosis, one report shows that atherosclerotic lesion area, necrotic area and macrophage infiltration are decreased." (PMID 31953345, 2020). "As RIPK3 is necessary for necroptosis – and as necroptosis is considered to be inherently inflammatory – researchers have suggested that RIPK3 or MLKL should be targeted to decrease atherosclerosis severity in the clinical setting." (PMID 31953345, 2020). "This conditional deletion of RIPK3 aids in understanding how cell-specific RIPK3 inhibition affects atherosclerosis and gives insight into the consequences of targeting components of the necroptosis pathway in a disease context." (PMID 31953345, 2020). "This raises questions about the contribution of microbiota to RIPK3-dependent functions within the context of atherosclerosis." (PMID 31953345, 2020). "Bone marrow transplantation revealed that loss of RIPK3 from bone marrow derived cells was sufficient to recapitulate the athero-protective phenotype observed in Ripk3−/− mice, suggesting that hematopoietic cell-specific RIPK3 may play an important role in atherosclerosis progression." (PMID 33142926, 2020). "Overall, these findings clearly illustrate a role for RIPK3-mediated macrophage necroptosis in atherosclerosis." (PMID 31019462, 2019). "Inhibition of RIPK3 or RIPK1 played a protective role from conditions such as atherosclerosis, renal ischemia reperfusion, and renal graft rejection." (PMID 29527209, 2018). "Therefore, RIPK1 and RIPK3 are closely related to the onset and progression of atherosclerosis and inflammation‐mediated stroke." (PMID 39657719, 2024). "In patients with atherosclerosis, the expression levels of RIPK3 protein and MLKL are elevated." (PMID 39301029, 2024). "Moreover, drugs or inhibitors targeting RIPK1 and RIPK3 can be designed to slow down atherosclerosis progression by mitigating macrophage necroptosis." (PMID 35087837, 2021). "Recent evidence from our lab indicates that RIPK3 expression must be tightly regulated in endothelial cells to promote angiogenesis, to maintain vascular integrity during embryogenesis, and to provide protection from postnatal atherosclerosis." (PMID 34153072, 2021). "Novel insights about RIPK3 in atherosclerosis emerge endlessly." (PMID 34867386, 2021). "However, RIPK3 has been connected to numerous other cellular pathways, which raises questions about its actual role in atherosclerosis." (PMID 31953345, 2020).